MIRLET7C (microRNA let-7c)
Synonyms: hsa-let-7c; LET7C; MIRNLET7C; let-7c
Gene: MicroRNA gene on chromosome 21 (16,539,828 to 16,539,911, forward strand). Ensembl gene ENSG00000199030.
Gene Ontology:
Biological process: miRNA-mediated post-transcriptional gene silencing
Cellular component: RISC complex
Homologues: Orthologues: chimpanzee ptr-let-7c (100% identical), macaque MIRLET7C (95% identical), mouse Mirlet7c-1 (95% identical), rat Mirlet7c1 (95% identical), guinea pig MIRLET7C (94% identical), pig ssc-let-7c (94% identical), tropical clawed frog xtr-let-7c (92% identical), zebrafish mirlet7c-2 (89% identical), zebrafish mirlet7c-1 (88% identical). Paralogues in human: MIRLET7A2 (75% identical), MIRLET7E (69% identical), MIRLET7A1 (67% identical), MIR98 (64% identical), MIRLET7D (64% identical), MIRLET7F2 (64% identical), MIRLET7A3 (63% identical), MIRLET7F1 (60% identical), MIRLET7G (55% identical), MIRLET7I (54% identical).
Diseases named in the same sentence as MIRLET7C in open-access papers:
MIRLET7C is named in the same sentence as 3 diseases in open-access papers, as found by Europe PMC text mining. Sharing a sentence is not in itself a finding about the gene and the disease.
MIRLET7C shares sentences with these, for which no sentence is quoted: cancer (1 paper); teratospermia (1); tumor (1).